IDH1 (isocitrate dehydrogenase (NADP(+)) 1)
Diseases named in the same sentence as IDH1 in open-access papers (continued):
Sharing a sentence is not in itself a finding about the gene and the disease.
glioma (continued). "Interestingly, recent studies have shed light on the potential role of tumor molecular markers, such as IDH1 mutation and MGMT methylation in seizure occurrence in patients with gliomas." (PMID 36831869, 2023). "This hypothesis was tested by expressing mutant IDH1 with a point alteration—converting arginine 132 to histidine—within glioma cell lines that contain wild-type IDH1." (PMID 37218937, 2023). "Indeed, AG-881 is currently under a phase 1, open-label, dose-escalation and expansion trial for the safety and pharmacokinetic properties to be investigated in both IDH1 and IDH2 mutated gliomas." (PMID 37296846, 2023). "Both IDH1 and IDH2 are somatically mutated in AML predominantly showing hotspot mutations, colon cancer, glioma, enchondromas, spindle cell hemangiomas, osteosarcoma, glioblastoma, chondrosarcomas, intrahepatic cholangiocarcinoma, prostate cancer, and B-acute lymphoblastic leukemia." (PMID 37371524, 2023). "In conclusion, the data in this and previous studies suggest that the increased risk of IDH1-mutated glioma conferred by rs11706832 is not caused by an effect on the LRIG1 expression level." (PMID 37185361, 2023). "In this study, IDH1 gene mutation was detected in 86 cases (74.8%), IDH2 gene mutation in five cases (4.4%) and TERT promoter mutation in 68 cases (59.1%), the results showed that IDH1/2 and TERT genes were related factors affecting the prognosis of patients with glioma." (PMID 37250582, 2023). "The differential expression of the LDHA protein, a key glycolytic enzyme, in different molecular phenotypes of IDH1 may lead to heterogeneity in glycolytic energy metabolism in glioma cells and may affect glioma cell migration, invasion, and proliferation." (PMID 37066523, 2023). "Glioma cells engineered to express mutant IDH1 produced D-2-hydroxyglutarate as expected." (PMID 37218937, 2023). "These include a phase III trial studying vorasidenib versus a placebo in patients with residual or recurrent IDH mutant gliomas grades 2 or 3 (NCT04164901) and a study of DS-1001 in patients with chemotherapy- and radiotherapy-naïve IDH1-mutated WHO grade 2 gliomas (NCT04458272)." (PMID 37060388, 2023). "With the finding that histone deacetylase inhibitors may be promising therapeutics, we performed a multi-omics approach to determine the effect of HDAC inhibitors on the chromatin structure of IDH1 mutant gliomas." (PMID 37528157, 2023). "Recent drug screens have shown that IDH1 mutant gliomas may be especially sensitive to these compounds." (PMID 37528157, 2023). "Work is ongoing to evaluate the reproducibility of these findings in a larger cohort of patients with low or high-grade gliomas, in addition to comparing the specificity of CSF D-2-HG versus imaging or IDH1 ddPCR from cell-free DNA for delineating pseudoprogression from progression." (PMID 37313502, 2023). "Although IHC methods are routinely used in the clinic, several exome sequencing studies have demonstrated that traditional IDH1 antibody testing using IHC methods fails to detect up to 15% of IDH-mutated gliomas." (PMID 37760146, 2023). "1H MRS was applied to investigate wild-type IDH1 and mutant IDH1 glioma cells." (PMID 35262263, 2023). "In addition, previous studies have revealed cell subtypes that are associated with glioma progression, and EGFR, NF1, and PDGFRA/IDH1 are markers for the classical, mesenchymal, and proneural types, respectively." (PMID 37371484, 2023). "IDH1 and IDH2 mutations result in the production of reduced alpha-ketoglutarate (α-KG) levels and increased 2-hydroxyglutarate (2-HG), which influence histone and DNA methylation profiles in glioma." (PMID 36984785, 2023). "We observed a difference in the IDH1 status in a cohort of glioma patients." (PMID 37547724, 2023). "Based on these results, we speculated that lncRNA CRNDE played a role as an oncogene in glioma, and might through targeting miR-23b-3p regulating IDH1, which is the focus of our future work." (PMID 37934582, 2023).
glioma (continued). "Interestingly, IDH1-MUT gliomas, which are less aggressive than IDH1-WT gliomas, have low tumor neutrophil infiltration and downregulation of chemotaxis-related genes." (PMID 36594465, 2023). "One pertinent example is the glioma CpG island methylator phenotype (G-CIMP), a pattern of genetic changes that includes MGMT methylation, which is often associated with the presence of IDH1 or IDH2 gene mutations." (PMID 36831683, 2023). "Interestingly, mutations in the citric acid cycle genes, isocitrate dehydrogenase (IDH1/2), are common events in low-grade gliomas and acute myeloid leukemias." (PMID 38066546, 2023). "We did not identify an association of the T2FMM with IDH1 mutations in dogs, but this finding was not unexpected given the rarity in which IDH1 mutations have been identified in dogs with gliomas." (PMID 37246729, 2023). "Immunohistochemistry with IDH1 R132H mutant-specific antibodies is used as an alternative procedure for glioma classification, being particularly useful when direct sequencing cannot be implemented for economic or facility reasons or because of tissue resource limitations." (PMID 36810519, 2023). "Expression of most CD4 T subset-associated genes was also not significantly impacted by IDH1 mutation in low grade gliomas." (PMID 37161052, 2023). "As an initial step, we determined which HDAC genes are highly expressed in IDH1 mutant gliomas." (PMID 37528157, 2023). "GSC stemness is thought to be affected by IDH1 and IDH2 mutations in the glioma." (PMID 37894287, 2023). "Overall, the literature indicates that differences in neurocognitive status between IDH1 subgroups may reflect the differences in neuroplasticity, that is, the brain’s ability to adapt to a tumor, with IDH1-wt gliomas to allow a limited one." (PMID 36970174, 2023). "Molecular alterations characterizations such as isocitrate dehydrogenase IDH1/2 mutations, 1p/19q codeletion, and MGMT promoter methylation, have improved the accuracy of diagnostics, prognostics, and prediction of treatment response for glioma patients." (PMID 38071304, 2023). "Astrocytic gliomas with high-grade features (either histopathologic or molecular) without an IDH1/2 mutation are termed IDH1/2 wildtype glioblastomas." (PMID 37345193, 2023). "However, when the GL261 glioma cells with IDH1-R132H were transplanted into C57BL/6 J mice, the survival was improved." (PMID 37741882, 2023). "Glioblastoma multiforme (GBM), defined by the fifth edition of the World Health Organization (WHO) classification of tumors of the central nervous system as an isocitrate dehydrogenase 1/2 (IDH1/2) wild type (WT) diffuse glioma, is the most common and aggressive tumor of the central nervous system." (PMID 38260852, 2023). "An important example is INDIGO (NCT04164901), an ongoing randomized phase III study of vorasidenib, a promising oral inhibitor of IDH1/2 mutations that has shown a 30.8% objective response rate in non-enhancing glioma patients." (PMID 35957904, 2022). "They found that plasma cfDNA from 60% of the cases examined contained the mutation unlike plasma from IDH1WT gliomas that did not have detectable mutant IDH1 ctDNA." (PMID 36380861, 2022). "While many studies of glioma have historically combined IDH1/2 mutant and wild-type cohorts when analyzing treatment outcomes in glioma patients, recently, more concerted efforts have been made to analyze the outcomes of IDH1/2 mutant gliomas as a distinct entity." (PMID 35448183, 2022).
glioma (continued). "In contrast, IDH1 exhibited the highest mutation frequency in the low-aging CAF score group, which was consistent with the well-identified concept that IDH mutation was associated with better prognosis in gliomas." (PMID 36092895, 2022). "We hypothesized that combinations of genes IDH1/2, 1p19q, TERTp, EGFR, BRAF, TERTp, 10q, and H3 status can stratify gliomas for risk and may even be superior to conventional histological grading for prognostication." (PMID 35558510, 2022). "GBM, low-grade glioma, cholangiocarcinoma, acute myeloid leukemia (AML), chondrosarcoma, and melanoma have all been linked to IDH1 mutations." (PMID 35873570, 2022). "However, only 15 patients with Grade 2–3 gliomas (8 IDH1-mutant and 7 with wildtype) were selected for subsequent analysis of blood flow in the subgroups of mutant and wildtype gliomas." (PMID 35741254, 2022). "Further study warrants the development of WM17 as a therapeutic agent for IDH1-mutant gliomas." (PMID 36091829, 2022). "Mutation hotspots such as BRAFV600, IDH1R132, IDH2R172, and IDH2R140 are prime examples where identifying mutational status during surgery could inform more-aggressive resection (BRAF mutant) or less-aggressive resection (IDH1/2 mutant) of gliomas." (PMID 35840782, 2022). "By contrast, IDH1/2 wild-type glioma (IDHwt; without either of the mutations) is the most aggressive form of glioma, and IDHwt patients only have a short 6–12-month survival time." (PMID 35216362, 2022). "At present, IDH1 and 1p 19 q have become genetic indicators of molecular typing of gliomas, which further highlights the importance of molecular typing in the individual diagnosis and treatment of gliomas." (PMID 36504559, 2022). "Importantly, wild-type IDH1 was correlated with much worse clinical outcomes in patients with gliomas." (PMID 34992215, 2022). "Studies have shown that mutation in the IDH1 gene, especially the R132H mutation, can promote NK cell recruitment through CX3CL1/CX3CR1 chemotherapy and are associated with a better prognosis in gliomas." (PMID 35601497, 2022). "Although no obvious glioma cells were identified, immunohistochemistry (IHC) for the canonical isocitrate dehydrogenase 1 (IDH1) R132H mutation revealed unequivocally positive cells with long, ramified processes." (PMID 35128400, 2022). "The activated LXRs enhances cholesterol efflux and decreases cholesterol influx by upregulating ApoE, resulting in the cholesterol de novo synthesis and the alteration of cholesterol homeostasis in IDH-1 mutant glioma cells, which further contributes to glioma progression." (PMID 36506554, 2022). "IDH1/2 mutation, 1p/19q codeletion, TERT promoter mutation and several other markers are used to define glioma subtypes." (PMID 35873494, 2022). "For instance, in low-grade gliomas, the IDH1/2 is a significant target." (PMID 35912242, 2022). "Isocitrate dehydrogenase 1 (IDH1) mutation information is crucial for diagnosis, prognosis and guidance in clinical decisions due to observation that IDH1 mutated gliomas have an improved overall survival rate rather than with IDH1 wild type." (PMID 36503979, 2022). "Gliomas with mutations in isocitrate dehydrogenase (IDH) 1 and 2, first discovered in genomic analysis of GBM, are a molecularly distinct subtype of diffuse glioma associated with younger age of diagnosis and longer overall survival compared to IDH1/2 wild-type gliomas." (PMID 35448183, 2022). "Meanwhile, aromatic sulfonamide compounds did not affect the growth of BXD-3752 glioma cells without IDH1 mutation, which indicates that aromatic sulfonamide compounds will have a higher selectivity for IDH1 mutated glioma cells." (PMID 36091829, 2022). "Only 1 case in each arm was newly diagnosed, and all patients harbored an IDH1 mutation, though this was not required for eligibility, and 1 patient received neoadjuvant vaccine prior to glioma diagnosis." (PMID 34882581, 2022).
glioma (continued). "In six patient-derived IDH1-mut primary glioma cultures, IDH1-mut glioma cells have proven to be very sensitive to two different BET inhibitors in vitro (the well-established JQ1 compound and GS-626510), with an IC50 value less than 250 nM and achieving maximum cell death of 31 to 77%." (PMID 35267433, 2022). "Noticeably, most IDH1 and 1p/19q codeletion mutations occurred in the group with low immune scores, indicating that IDH mutations and 1p/19q codeletion negatively correlate with glioma immunity." (PMID 35265085, 2022). "DNA methylation inhibitors showed promise in xenografts derived from IDH1-mutant gliomas." (PMID 36230865, 2022). "Ki-67 expression increased gradually from grades I to IV and was significantly higher in HGG patients than in LGG patients (P <0.05), regardless of glioma type, IDH1 mutation, or wild type." (PMID 36147928, 2022). "IDH2 is often considered to have a similar prognostic effect to IDH1 in glioma." (PMID 35812244, 2022). "Friebel and coworkers showed in a single-cell transcriptomic study that CD16-positive NK cells primarily accumulate in IDH1 mutated gliomas and further in those with negative MGMT promoter methylation status." (PMID 36361720, 2022). "Moreover, in a phase I clinical trial, DS-1001b was well tolerated with favorable brain distribution, and recurrent/progressive IDH1 mutant glioma patients responded to treatment." (PMID 35628161, 2022). "Interestingly, it is reported that only IDH1/2 wild-type gliomas (59% GBMs and 41% LGGs) highly expressed MEOX2 compared with IDH1/2-mutated gliomas in TCGA dataset." (PMID 35646656, 2022). "Interestingly, in IDH1-mutant gliomas, 2-HG can activate NF-κB, regulate CX3CL1 expression, and then CX3CL1 recruits NK cells to the tumor location." (PMID 35769466, 2022). "The slow-growing primary brain tumors, WHO grade II and III gliomas (hereon, referred to as, lower-grade gliomas) are diagnosed based on molecular features (presence or absence of IDH1/2 mutations and 1p/19q co-deletion)." (PMID 35645972, 2022). "Results suggest that FLAIR volume, nrCBV, and ADC measurements may be useful early imaging biomarkers for assessing IDH inhibitor treatment response in human IDH1-mutant gliomas." (PMID 36033919, 2022). "Interestingly, a recent investigation revealed that the TS pathway can be also targeted in IDH1 mutant gliomas by unbalancing the antioxidant homeostasis of the tumor." (PMID 34856072, 2022). "In particular, isocitrate dehydrogenase 1 and 2 (IDH1 and IDH2) mutation and 1p/19q codeletion have been recognized as promising predictive molecular markers, resulting in their inclusion in the 2016 World Health Organization (WHO) classification of gliomas." (PMID 35053475, 2022). "The inclusion of more patients with IDH1/2 and ATRX mutations in the low-risk group and more patients with EGFR mutations in the high-risk group indicates that BM-gene-related risk scores can distinguish glioma patients with different prognoses." (PMID 36292695, 2022). "In terms of methylation and copy number profile, as well as histological appearance and molecular signature, a novel IDH1-WT GBM methylation subgroup that differs from previously reported molecular subgroups was recently introduced in the classification of glioma." (PMID 36276147, 2022). "That approach has also been tested in IDH1‐mutant cancers, although in the present work, we observed how IDH1‐wild‐type gliomas were as sensitive as mutant gliomas to cysteine/cystine deprivation and that inhibiting IDH1‐mutant activity did not affect the response of those cells to this approach." (PMID 34856072, 2022).
glioma (continued). "ASL perfusion showed high values of sensitivity and specificity in the differential diagnosis of gliomas with distinct IDH1 status (for TBF: specificity 75%, sensitivity 77.6%, AUC 0.783, cutoff 80.57 mL/100 g/min, for nTBF: specificity 77.1%, sensitivity 79.3%, AUC 0.791, cutoff 4.7)." (PMID 35741254, 2022). "Evidently, only can the alteration in the frequency of the non-epigenetic and misincorporated DNA 6mA discriminate all types of human glioma (Astrocytoma, Anaplastic Astrocytoma, and Glioblastoma) from normal brain tissues regardless of IDH1 mutation." (PMID 35501312, 2022). "Although these patients showed significantly higher levels of D-2HG compared to leukemia or glioma patients harboring IDH1/2 mutations, they do not have a predisposition to developing gliomas, leukemia or other malignancies." (PMID 35804976, 2022). "Using a in vivo model of IDH1‐mutant glioma, we test the hypothesis that dietary cysteine/cystine restriction for cancer cells contributes to improved survival." (PMID 34856072, 2022). "We included this group of gliomas because in China they receive the same treatment as non-mutated IDH1 gliomas." (PMID 36614997, 2022). "IDH1 and IDH2 mutations were subsequently found in patients with WHO grade II/III gliomas." (PMID 36290819, 2022). "In gliomas, its occurrence seems to be independent of IDH1/IDH2 somatic mutations, while an inverse correlation with EGFR amplification has been suggested, but not confirmed, in an independent validation series." (PMID 36011350, 2022). "Secondly, in glioma, current studies recognize that IDH1 mutations are closely associated with glioma grade and prognosis, however, there is a lack of molecules associated with IDH1." (PMID 36504559, 2022). "The question that this study did not solve is, for low-grade gliomas that are negative for IDH1/IDH2 mutations, what is the source gene event?" (PMID 35747806, 2022). "The combination of two methods, MSP and qMSP, within the homogenous cohort (IDH1/2wt patients older than 50 years and with surgically resected glioma) gave significant relevance to the prognostic value of the MGMT promoter methylation status in Serbian diffuse glioma patients." (PMID 36361838, 2022). "Further, a patient with IDH1 (R132H) glioma was detected to have IgG1 subclass-specific antibodies 25, anti-IDH vaccines might be a viable new treatment strategy." (PMID 36263174, 2022). "In recent years, significant progress has been made to identify molecular markers that could predict the glioma’s progression and clinical prognosis, such as IDH1, 1p19q, and MGMT methylation." (PMID 35274175, 2022). "In addition, mutations in genes encoding isocitrate dehydrogenases 1 and 2 (IDH1 and IDH2) are also found in low grade gliomas (grades II and III) and secondary GBMs (GBM, IDH-mutant)." (PMID 35455961, 2022). "Furthermore, the nucleotide synthesis utilization and DNA repair capacity is different in IDH1-mut and IDH1-WT glioma." (PMID 34941573, 2022). "Although several new molecules such as IDH1 mutation, MGMT promoter methylation, and 1p/19q chromosome codeletion have been applied for diagnosis and treatment in gliomas, the prognosis of patients remains unsatisfactory, which drives us to explore more effective and credible factors." (PMID 36281290, 2022). "Among multiple types of cancers, IDH1 or/and IDH2 mutations have been identified, inter alia, in acute myeloid leukemia (AML), gliomas, chondrosarcoma, intrahepatic cholangiocarcinoma, thyroid carcinoma, and also rarely in prostate cancer, melanoma, and paraganglioma." (PMID 35628385, 2022). "Our results suggest that LITT is an effective treatment option for IDH1/2 mutant glioma." (PMID 35448183, 2022).